TRIM32 (tripartite motif containing 32)
Diseases named in the same sentence as TRIM32 in open-access papers (continued):
Sharing a sentence is not in itself a finding about the gene and the disease.
Sepsis (3 papers, 2019 to 2024). Sepsis is defined as life-threatening organ dysfunction caused by a dysregulated host response to infection. "Trim32 deficiency remarkably reduced bacteremia and proinflammatory cytokine secretion in mice with severe Lm infection, preventing sepsis." (PMID 37415157, 2023). "Collectively, TRIM32 aggravated Lm-induced sepsis in mice at early stages of infection, which was associated with increased cytokine production, decreased leucocyte recruitment and iNOS production." (PMID 37415157, 2023). "Intriguingly, in the context of sepsis, eCIRP impedes the interaction between TRIM32 and ZBP1, suppresses TRIM32-mediated polyubiquitination and proteasomal degradation of ZBP1, and thereby stabilizes its expression." (PMID 39465383, 2024). "Overall, our findings show that TRIM32 modulates innate immune response and iNOS production in macrophages, assisting the host in fighting Lm-induced sepsis at the early stages of infection." (PMID 37415157, 2023). "The role of TRIM32 in the pathogenesis of Lm-induced sepsis in mice was investigated in this study." (PMID 37415157, 2023). "TRIM32 is an intriguing host therapeutic target for the treatment of Lm-induced sepsis." (PMID 37415157, 2023). "Critically, during sepsis, internalized eCIRP in PVECs disrupts the interaction between ZBP1 and TRIM32, impeding proteasomal degradation of ZBP1 while stabilizing it." (PMID 39465383, 2024). "IP results demonstrated an increase in ZBP1 polyubiquitination levels upon LPS stimulation, while the addition of eCIRP significantly reduced the LPS-induced polyubiquitination of ZBP1 by Ub-TRIM32, underscoring eCIRP’s inhibitory effect on ZBP1 ubiquitination during sepsis." (PMID 39465383, 2024). "We found no significant inductions of Trim32 in the DIA or TA during sepsis, and little is known about its expression or importance in sepsis‐induced skeletal muscle atrophy." (PMID 31660704, 2019). "Trim32 levels in the DIA and TA were not affected by sepsis." (PMID 31660704, 2019).
acute myeloid leukemia (2 papers, 2022 to 2025). Acute myeloid leukemia (AML) is a group of neoplasms arising from precursor cells committed to the myeloid cell-line differentiation. "Studies have verified that high expression of TRIM32 is related to a poor prognosis of acute myeloid leukemia by using TCGA and GEO databases and clinical sample data." (PMID 40507857, 2025).
autism (2 papers, 2022 to 2024). Persistent deficits in social interaction and communication and interaction as well as a markedly restricted repertoire of activity and interest as well as repetitive patterns of behavior. "Rare copy number variation analysis has shown that the loss of TRIM32 gene is strongly associated with autism and attention deficit hyperactivity disorder." (PMID 35159260, 2022). "Therefore, all these abnormal processes can eventually lead to an E/I imbalance, which in turn causes autism-like behaviours in TRIM32−/− mice." (PMID 35159260, 2022).
cardiac hypertrophy (2 papers, 2016 to 2019). "We generated mice and isolated NRCMs (neonatal rat cardiomyocytes) that overexpressed or were deficient in TRIM32 to investigate the effect of TRIM32 on AB (aortic banding) or AngII (angiotensin II)-mediated cardiac hypertrophy." (PMID 26884348, 2016). "TRIM32-global-KO mice were generated to explore further the effect of TRIM32 deficiency on cardiac hypertrophy and heart failure in vivo." (PMID 26884348, 2016). "Altogether, these data suggest that TRIM32 deficiency correlates with the development of cardiac hypertrophy and heart failure." (PMID 26884348, 2016). "On the basis of the decline in TRIM32 expression observed in hypertrophic hearts, we hypothesize that TRIM32 deficiency is associated with the progression of pathological cardiac hypertrophy, thus cardiac overexpression of TRIM32 may be protective." (PMID 26884348, 2016). "In addition, mice and isolated NRCMs (neonatal rat cardiomyocytes) with either overexpression or deletion of TRIM32 were generated to investigate the role and underlying mechanisms of TRIM32 in cardiac hypertrophy." (PMID 26884348, 2016). "According to these data, we speculate that TRIM32-mediated prevention of pathological cardiac hypertrophy is associated with blockade of Akt-dependent signalling." (PMID 26884348, 2016). "The present study is the first to demonstrate that TRIM32 protects against pathological cardiac hypertrophy by repressing Akt-dependent signalling pathways." (PMID 26884348, 2016). "To elucidate the mechanisms by which TRIM32 plays a cardioprotective role in cardiac hypertrophy and heart failure, we next examined the status of the MAPK and Akt signalling pathways, which are known to be involved in pathological cardiac hypertrophy." (PMID 26884348, 2016). "This study presents the first evidence that TRIM32 protects against pathological cardiac hypertrophy by suppressing Akt-dependent signalling pathways." (PMID 26884348, 2016). "TRIM32 expression is decreased in the development of pathological cardiac hypertrophy and heart failure." (PMID 26884348, 2016). "In the present study, we aimed to delineate the potential function of TRIM32 in pressure overload-induced cardiac hypertrophy and heart failure using genetic manipulation of TRIM32 expression both in vivo and in vitro." (PMID 26884348, 2016). "Although the precise mechanisms are elusive, there is a potential explanation for the decreased TRIM32 content during the progression of cardiac hypertrophy." (PMID 26884348, 2016). "We provide evidence that TRIM32 overexpression attenuates cardiac hypertrophy and subsequent fibrosis by repressing PI3K/Akt signalling, whereas TRIM32 deficiency conferred the opposite phenotype in response to myocardial pressure overload." (PMID 26884348, 2016). "To the best of our knowledge, we provide the first evidence that TRIM32 is a negative regulator of cardiac hypertrophy under pathological conditions." (PMID 26884348, 2016). "Taken together, our results identify TRIM32 as a novel negative regulator of pathological cardiac hypertrophy, mainly through its suppressive action on PI3K/Akt signalling." (PMID 26884348, 2016). "Consistent with deterioration of pathological cardiac hypertrophy, TRIM32-KO mice exhibited more significant ventricular dilation compared with WT mice, as indicated by further increase in LVEDD and LVESD." (PMID 26884348, 2016). "To investigate whether compensatory overexpression of TRIM32 in hearts would alleviate pressure overload-induced cardiac hypertrophy and heart failure in vivo, we generated TG mice with cardiac-specific TRIM32 overexpression." (PMID 26884348, 2016). "To study the potential role of TRIM32 in the development of cardiac hypertrophy and heart failure, we first assessed whether cardiac TRIM32 expression levels were altered in failing human heart samples." (PMID 26884348, 2016).
cardiac hypertrophy (continued). "Furthermore, the results of the present study provide convincing evidence to support the concept that TRIM32 limits the development of cardiac hypertrophy, fibrosis and subsequent heart failure by interruption of the Akt-dependent signalling pathway." (PMID 26884348, 2016). "Thus these findings imply that TRIM32 represents a potential therapeutic target for the prevention of pathological cardiac hypertrophy." (PMID 26884348, 2016). "Given the similarity between skeletal muscle cells and cardiomyocytes, it is tempting to speculate that TRIM32 would be cardioprotective during cardiac hypertrophy." (PMID 26884348, 2016). "As TRIM32 expression was decreased during the development of cardiac hypertrophy and heart failure, we investigated whether TRIM32 could modulate the progression of cardiac hypertrophy." (PMID 26884348, 2016). "These in vitro data indicate that TRIM32 may act as a negative regulator of pathological cardiac hypertrophy." (PMID 26884348, 2016). "Collectively, these data indicate that the inhibitory effect of TRIM32 on pathological cardiac hypertrophy may be dependent, at least partially, on the regulation of Akt activity." (PMID 26884348, 2016). "Collectively, TRIM32 deficiency did not lead to pathological alterations at baseline, but remarkably enhanced the susceptibility of the heart to cardiac hypertrophy and heart failure induced by pressure overload." (PMID 26884348, 2016). "However, whether TRIM32 is involved in cardiac hypertrophy induced by biomechanical stresses and neurohumoral mediators remains unclear." (PMID 26884348, 2016). "Therefore TRIM32 could be a novel therapeutic target for the prevention of cardiac hypertrophy and heart failure." (PMID 26884348, 2016). "Therefore TRIM32 might be a potential therapeutic strategy for the prevention and treatment of cardiac hypertrophy and heart failure." (PMID 26884348, 2016). "First, we examined the effects of TRIM32 on the MAPK signalling pathways, which have been well documented to play an important role in cardiac hypertrophy." (PMID 26884348, 2016). "However, the role of TRIM32 in cardiac hypertrophy and heart failure has not yet been established." (PMID 26884348, 2016).
heart failure (2 papers, 2016 to 2022). Inability of the heart to pump blood at an adequate rate to meet tissue metabolic requirements. "In the present study, we observed that TRIM32 expression was progressively reduced from maladaptive hypertrophy to heart failure induced both by mechanical overload and by neurohumoral stimuli." (PMID 26884348, 2016).
inflammatory skin disease (2 papers, 2024 to 2025). Inflammatory skin disorders covers a broad category that includes many conditions ranging in severity, from mild itching to grave medical health complications These disorders are common in people of all ages and races. "Tripartite motif-containing protein 32 (Trim32), which acts as an E3 ubiquitin-protein ligase, is essential for multiple immune processes, including antiviral responses, innate immune responses, and inflammatory skin disorders." (PMID 40021897, 2025). "Among other genes related to the immune system are TRIM32 or STOM, and altered innate immunity is a feature of certain inflammatory skin diseases." (PMID 39199954, 2024).
Lafora disease (2 papers, 2011 to 2021). Lafora disease (LD) is a rare, inherited, severe, progressive myoclonic epilepsy characterized by myoclonus and/or generalized seizures, visual hallucinations (partial occipital seizures), and progressive neurological decline. "Twenty-one of the thirty-seven Lafora disease missense mutations in malin contained a conserved amino acid in TRIM32." (PMID 21798009, 2011). "Several of them are implicated in rare genetic diseases, and mutations in TRIM32 and TRIM-like malin are associated with Limb-Girdle Muscular Dystrophy R8 and Lafora disease, respectively." (PMID 33917450, 2021). "In order to determine whether malin and TRIM32 could have redundant functions, we first studied a physiological substrate of malin that is related to alterations found in Lafora disease." (PMID 21798009, 2011).
medulloblastoma (2 papers, 2020 to 2021). A malignant, invasive embryonal neoplasm arising from the cerebellum. "Knockout of Trim32 resulted in a higher incidence of medulloblastoma formation in the Ptch1 ± mice and the upregulation of SHH target genes, suggesting a tumor suppressor effect from antagonizing SHH signaling." (PMID 33273457, 2020).
mood disorder (2 papers, 2015 to 2022). A cognitive disorder a disturbance in which the person's mood is hypothesized to be the main underlying feature. "TRIM32 has been shown to cause declines in olfactory performance and deregulation of metabolomic pathways associated with mood disorders." (PMID 36297015, 2022). "In summary, our study provides comprehensive data on how the impairment of neurogenesis caused by the loss of the cell fate determinant TRIM32 causes a decrease of olfactory performance as well as a deregulation of metabolomic pathways that are linked to mood disorders." (PMID 25852471, 2015).
Obesity (2 papers, 2011 to 2025). Accumulation of substantial excess body fat. "Based on these findings, we propose that the TRIM32-INSR to be a potential site for pharmacological interventions as an effective therapy in mitigating obesity-induced hepatic insulin resistance, associated fatty liver disease, and dyslipidemia." (PMID 39747658, 2025). "Other mutations in the TRIM32 gene are related to the Bardet-Biedl syndrome type 11 (BBS11, OMIM 209900), whose symptoms include obesity, retinophaty, kidney and heart abnormalities and cognitive deficiency." (PMID 21798009, 2011). "In conclusion, our study showed that obesity induced by a high-fat diet triggers two significant responses: first, it inhibits the AMPK-dependent Ser372 phosphorylation of SREBP-1c, consequently enhancing the transcriptional activity of TRIM32." (PMID 39747658, 2025).
retinal ciliopathies (2 papers, 2019 to 2021). "So far, mutations in two UPS genes, both encoding E3 ubiquitin ligases, have been unequivocally determined as causative genes for inherited retinal ciliopathies in humans: TOPORS, causative of non-syndromic autosomal dominant RP, and TRIM32/BBS11, causative of syndromic autosomal recessive BBS." (PMID 33748110, 2021).
Salmonella Infections (2 papers, 2015 to 2018). Infections with bacteria of the genus SALMONELLA. "In addition, the T3SS effector SseK3 is relevant to Salmonella infection through a novel molecular interaction with an E3 Ub ligase, TRIM32." (PMID 29594070, 2018). "Ectopically expressed SseK3 partially co-localises with TRIM32 at the trans-Golgi network, but SseK3 is not recruited to Salmonella induced vacuoles or Salmonella induced filaments during Salmonella infection." (PMID 26394407, 2015).
skin cancer (2 papers, 2021 to 2022). "According to previous studies, aberrant overexpression of TRIM32 was depicted in human skin cancer cells." (PMID 35756612, 2022). "Tripartite Motif Containing 32 (TRIM32) a RING protein, is overexpressed in several tumors, including skin tumors." (PMID 33921128, 2021).
tuberculosis (2 papers, 2023 to 2024). A chronic, recurrent infection caused by the bacterium Mycobacterium tuberculosis. "Overall, these findings suggest that TRIM32 plays an important role in the host response to Mtb infection through the induction of autophagy, representing a promising target for host-directed tuberculosis therapies." (PMID 37543647, 2023). "This suggests that TRIM32 is a potential target for host-directed tuberculosis therapies." (PMID 38225560, 2024). "Notably, TRIM32 expression has been reported to decrease leukocytes from tuberculosis patients with tuberculosis compared to healthy controls and subjects with tuberculosis infection." (PMID 38225560, 2024). "The expression or activity of TRIM32 may serve as a biomarker for stratifying tuberculosis stages or as a target for host-directed therapies." (PMID 38225560, 2024).
type 2 diabetes (2 papers, 2023 to 2025). "TRIM32 has been identified as a critical E3 ubiquitin ligase contributing to type 2 diabetes pathogenesis through distinct, tissue‐specific mechanisms." (PMID 41362701, 2025).
acute kidney injury (1 paper, 2025). Sudden and sustained deterioration of the kidney function characterized by decreased glomerular filtration rate, increased serum creatinine or oliguria. "In a gentamicin-induced acute kidney injury experiment in rats, expression of MuRF1 and MAFbx was increased in muscle and correlated with AKI severity, whereas the expression of the other three E3 ligases (Nedd4, Trim32, and Fbxo30 / MUSA1) was irrelevant." (PMID 40225869, 2025).
amyotrophic lateral sclerosis (1 paper, 2021). Amyotrophic lateral sclerosis (ALS) is a neurodegenerative disease characterized by progressive muscular paralysis reflecting degeneration of motor neurons in the primary motor cortex, corticospinal tracts, brainstem and spinal cord. "Amyotrophic lateral sclerosis (ALS), a progressive and fatal motor neuron disease, is also correlated with TRIM32." (PMID 34421574, 2021).
anxiety disorder (1 paper, 2023). A category of psychiatric disorders which are characterized by anxious feelings or fear often accompanied by physical symptoms associated with anxiety. "First, TRIM32 was strongly associated with anxiety disorders based on a study of copy number variants." (PMID 36514243, 2023).
Bardet-Biedl syndrome 11 (1 paper, 2014). Any Bardet-Biedl syndrome in which the cause of the disease is a mutation in the TRIM32 gene. "For example, TRIM32 (UniProtKB/Swiss-Prot accession Q13049) has been shown to cause Bardet–Biedl syndrome 11 (BBS11)." (PMID 24848695, 2014).
calpainopathy (1 paper, 2021). "Although the pathophysiology of calpainopathy has not been fully elucidated yet, some experimental and bioinformatic results show that CAPN3 targets the E3 ubiquitin proteins MuRF1 and TRIM32 as substrates." (PMID 35366260, 2021).
cerebellar degeneration (1 paper, 2021). Degeneration of the cerebellum. "In the present study, we found the reduced size of the cerebellum, loss of PCs, decreased in dendritic arborization, and spines density of PCs, which suggested that cerebellar degeneration was likely occurred in mid-age TRIM32−/– mice." (PMID 34421574, 2021).
Cognitive impairment (1 paper, 2021). Abnormal cognition is characterized by deficits in thinking, reasoning, or remembering. "This discrepancy in phenotypes suggests that cognitive impairment should be associated with ASTN2 loss of function rather than TRIM32 loss of function." (PMID 33485293, 2021).
dilatation (1 paper, 2016). "Our data demonstrate that TRIM32 overexpression protected hearts from pathological hypertrophy, fibrosis, ventricular dilatation and dysfunction induced by chronic pressure overload." (PMID 26884348, 2016).
head and neck squamous cell carcinoma (1 paper, 2025). A squamous cell carcinoma that arises from any of the following anatomic sites: lip and oral cavity, nasal cavity, paranasal sinuses, pharynx, larynx, and salivary glands. "Studies have shown that the carcinogenesis of TRIM32 is related to its promotion of ubiquitination and degradation of Abi2, which impacts cell growth, migration, and transformation, and the expression of TRIM32 is elevated in human head and neck squamous cell carcinoma." (PMID 40507857, 2025).